PAK1 (p21 (RAC1) activated kinase 1)
Diseases named in the same sentence as PAK1 in open-access papers (continued):
Sharing a sentence is not in itself a finding about the gene and the disease.
tumor (223 papers, 2008 to 2026). "PAK1 levels in primary tumor tissues were also found to be associated with a good differentiation degree and longer survival, contrary to other studies in the literature." (PMID 40864802, 2025). "Amplification of the PAK1 gene and high levels of PAK1 protein are often associated with poor clinical prognosis, invasive tumor characteristics, and resistance to therapy." (PMID 40001545, 2025). "Increased PAK1 expression is often associated with poor clinical prognosis, invasive tumor characteristics, and therapeutic resistance." (PMID 40001545, 2025). "Bioinformatics analysis has shown that several proteins interacting with MES are strongly associated with tumor progression, including PAK1, TNF, SRC, and CDC25A." (PMID 40699726, 2025). "In studies conducted on gastrointestinal system cancers, it has been stated that PAK1 expression and activity are associated with the aggressive behavior of the tumor." (PMID 40864802, 2025). "PAK1 amplification has been associated with advanced tumour stages, higher MVD, and notable colony stimulating factor 2 expression (CSF2) in myxofibrosarcoma." (PMID 38067120, 2023). "Pearson’s x2 test was performed to assess associations between PAK1 CN and tumour features, and between PAK1 and CCND1 CNs." (PMID 37368917, 2023). "In a xenografted model of prostate cancer, inhibition of PAK1 decreased tumour growth, which was associated with a 70% reduction in laminin-positive blood vessels." (PMID 38067120, 2023). "In the context of tumor therapy, for example, PAK1 triggers DNA repair caused by genotoxic therapeutic agents." (PMID 35206009, 2022). "And study shows associations between PAK1 expression and subcellular localization in tumor cells and tamoxifen resistance." (PMID 29179495, 2017). "Even though the deregulation of PAK1 is closely associated with various human diseases, and PAK1 plays a crucial role in tumor genesis, progression, invasion and metastasis in several types of human tumor." (PMID 28186966, 2017). "Our present study revealed that upregulation of PAK1 kinase activity conferred stem-like phenotype via NF-κB/IL-6 activation in vitro and in vivo that defines a novel potential mechanism underlying tumor metastasis and sunitinib resistance in RCC patients." (PMID 25675297, 2015). "We observed that PAK1 overexpression was significantly associated with tumor location, lymph node metastasis and reduced overall survival, and PAK1 expression is also associated with γH2AX." (PMID 26023713, 2015). "In particular, PAK1 and nuclear phospho-PAK1 were associated with advanced tumor grade and poor survival rate." (PMID 25093037, 2014). "Overexpression of PAK1 mRNA was found in 75% of tumorous tissues and associated significantly with the presence of venous invasion, poor cellular differentiation, advanced tumor stages as well as shorter disease-free survival." (PMID 25093037, 2014). "Our previous study showed that overexpression of p21-activated protein kinase 1 (PAK1) is frequently observed in HCC and is associated with a more aggressive tumor behavior, suggesting that PAK1 is a potential therapeutic target in HCC." (PMID 23894351, 2013). "PAK1 overexpression in tumor was associated with lymph node (LN) metastasis (P<0.001), advanced tumor stage (P<0.001), large tumor size (P = 0.006), residual surgical margin (P = 0.033), and unfavorable overall survival (P<0.001)." (PMID 24236193, 2013). "Additionally, the role of structural variants in PAK1 and the potential tumor‐suppressor functions of PAK5 and PAK6 represent important areas for future exploration." (PMID 39756822, 2025). "PAK1 abnormalities such as gene amplification leading to increased mRNA and protein expression, phosphorylation, and increased accumulation of the activated form of this enzyme have been linked to tumor prognosis." (PMID 37190165, 2023).
tumor (continued). "In addition, PAK1 facilitates the cross-talk between the Ras effector pathways and the Wnt signaling pathway that are associated with tumor progression, migration, and angiogenesis." (PMID 36033456, 2022). "A recent in vitro and in vivo study demonstrated that ivermectin induce cytostatic autophagy in breast cancer cells linked to the inhibition of PAK-1 expression leading to a reduced phosphorylation of Akt and blockage of Akt/mTOR signalling pathway inhibiting tumour growth." (PMID 33092251, 2020). "However, clinical studies have suggested that erbB2 and MEK signalling are linked via Pak1 (p21-activated kinase), a context that involved tumour cell-matrix interactions and is supported by our 3D data." (PMID 27251376, 2016). "PAK1 expression and activity are upregulated in different human tumors, such as breast, lung, colorectal, liver and kidney cancers, and are associated with tumor invasiveness, metastasis and poor prognosis." (PMID 25675297, 2015). "Several clinical and functional studies have implicated PAK1 in tumor metastasis." (PMID 26023713, 2015). "Considering we identified that PAK1 activation is closely correlated with E-cadherin and p120-catenin expression in our clinical samples, we were facing the question whether PAK1 activation establishes any association with tumor stage at presentation." (PMID 25956913, 2015). "High pPAK1 was observed in NF1-mutant, SUZ12-mutant ST88-14 MPNST cells independent of CRISPRi suppression of NF2, suggesting PAK1 activation may be conserved across de-differentiated Schwann cell tumors after loss of either tumor suppressors or epigenetic regulators." (PMID 38216572, 2024). "In addition, PAK1 is intimately linked to proper function and migration of a variety of cell types such as macrophages, fibroblasts, endothelial cells and tumor cells." (PMID 25379771, 2014). "We assessed the role of PAK1 in a large panel of human tumors (via high resolution, single-nucleotide polymorphism arrays and immunohistochemical staining) and in vivo tumor models (via inducible RNA interference) and showed that PAK1 inhibition resulted in improved anti-tumor efficacy." (PMID 21653999, 2011). "These evidences support PF-309's potential as an effective CRC therapy through targeting PAK1, as its anti-tumor effects are significantly diminished when PAK1 function is compromised." (PMID 41459112, 2026). "We also examined PAK1 protein expression in tumor tissue and found that staining intensity was higher in both WT and PAK1fl tumors as compared to normal tissue." (PMID 40783411, 2025). "PAK1 convergently regulates oncogenic signaling hubs, as evidenced by its inhibition inducing Ras-driven tumor regression and AKT suppression in vivo, validating its mechanistic role in KRAS-dependent phosphatidylinositol 3-kinase (PI3K)/AKT activation." (PMID 40302782, 2025). "Knockout of PAK1 or PAK4 inhibited angiogenesis within the tumour by decreasing the intra-tumoral expression of CD31 and CD34, two common endothelial cell markers responsible for angiogenesis." (PMID 40943273, 2025). "This was supported by proteomic profiles indicating the regulation of endothelial cell and leukocyte trans-endothelial migration in PAK1- or PAK4-knockout tumours." (PMID 40943273, 2025). "Future work in immune-competent and orthotopic humanised models will be critical to determine how PAK1- or PAK4-targeted interventions can affect the tumour vasculature, immune infiltration, and chemotherapy response in a clinically meaningful context." (PMID 41294859, 2025). "PAK1 inhibition promotes vascular normalisation and an immune-permissive tumour microenvironment (TME), whereas PAK4 inhibition enhances gemcitabine response by increasing vessel calibre and downregulating DNA repair pathways." (PMID 41228228, 2025). "The pharmacological inhibition of Pak1/Pak2 and silencing Pak1/Pak2 using siRNA reduced the tumor cell metabolism—reduced ECAR and OCR." (PMID 40090587, 2025).
tumor (continued). "Decreased vascular density was accompanied by increased tumour hypoxia, indicating impaired perfusion following PAK1 or PAK4 knockout." (PMID 40943273, 2025). "p21-activated kinase 4 (PAK4), a member of the PAK family (PAK1-6), was initially recognized for its role in tumor development." (PMID 41023133, 2025). "In the study published in 2013, PAK1 expression was observed to be much higher in cell lines with high invasive/metastatic potential than in early-stage tumor cell lines, while PAK6 expression was detected at similar levels in all cell lines." (PMID 40864802, 2025). "While PAK1 protein levels were at their lowest values in normal and benign hyperplasia tissues, they were found to be much higher in tumor and metastatic tissues." (PMID 40864802, 2025). "Although numerous scientific reports link Pak1 to tumorigenesis, there is a paucity of research exploring Pak1’s role in regulating tumor cell metabolism." (PMID 40090587, 2025). "PAK1 knockout inhibited angiogenesis within the tumour by decreasing the intra-tumoral expression of CD31 and CD34, two common endothelial cell markers responsible for angiogenesis." (PMID 41228228, 2025). "Subsequently, the analysis of p-PAK1S144 and total lysine acetylation levels demonstrated that ZMF-25 suppressed tumor growth by inhibiting PAK1 and HDAC class IIb." (PMID 40302782, 2025). "PAK1&4KO also suppressed the expression of fibronectin by PC cells more dramatically, contributing to overall decreased levels of fibronectin in the PAK1&4KO tumours." (PMID 41228228, 2025). "p21-activated kinase (Pak1), a serine-threonine kinase is found to be upregulated in many solid tumors and promotes tumor progression via diverse signaling pathways." (PMID 40090587, 2025). "PAK1 knockout reduced angiogenesis, suppressing tumour growth but decreasing gemcitabine efficacy, while promoting vascular normalisation and endothelial activation." (PMID 41228228, 2025). "In that study, inhibition of PAK1 downregulated PD-L1, an immune checkpoint ligand which suppresses anti-tumor immunity." (PMID 40783411, 2025). "Synergistic approaches, such as combining PAK1 inhibitors with immune checkpoint therapies, are also being explored to boost anti-tumor immunity." (PMID 40001545, 2025). "Inhibition of PAK1 or PAK4 enhances T cell activation in PC by stimulating anti-tumour immunity through downregulation of PD-L1." (PMID 41228228, 2025). "PAK1 is overexpressed in human IBD and CRC5,11,12and we have previously shown that total Pak1 deletion in a mouse model of IBD reduces tumor multiplicity upon AOM/DSS treatment." (PMID 40783411, 2025). "The fact that knockout of PAK1 or PAK4 reduced tumour vascularisation, thus vascular regression, while enhancing vasculature normalisation, indicates a key role of PAK1 or PAK4 in balancing vascular regression and normalisation." (PMID 40943273, 2025). "In order to gain a deeper understanding of the role of Pak1 in tumor cell metabolism, untargeted metabolomic analysis was carried out." (PMID 40090587, 2025). "Our study provides insights into the regulation of tumor cellular metabolism by Pak1, thereby promoting tumorigenesis." (PMID 40090587, 2025). "PAK1 is an established oncogenic protein kinase and its hyperactivation leads to tumor cell proliferation, migration, invasion, and survival." (PMID 40586933, 2025). "The data from the analysis of the proteomic profiles of PAK1KO and PAK4KO tumours have revealed that knockout of PAK1 or PAK4 upregulated ICAM-1, MHC class I molecules and enriched the expression of proteins involved in leukocyte trans-endothelial migration." (PMID 40943273, 2025). "We aimed to investigate the role of Pak1 in regulating the energy demands of continuously proliferating tumor cells." (PMID 40090587, 2025). "The results showed that compared to the LV-NC group, knocking down circPTPN22 resulted in a decrease in tumor weight and volume, slower growth rate, and reduced expression of PAK1 in the tumor." (PMID 38956466, 2024).
tumor (continued). "Our data suggests RhoJ as a potential novel molecular driver of tumor development in breast tissues and a mediator of cell resistance to conventional chemotherapy through PAK1 activation." (PMID 38247865, 2024). "ANKRD52 is a tumor suppressor that regulates PP6c-mediated PAK1 dephosphorylation, which inhibits proliferation." (PMID 38338859, 2024). "Tumor growth in mice injected with PAK1 Y3F, which is still kinase active, was strongly inhibited as compared to mice injected with PAK1 WT." (PMID 38660565, 2024). "It has been found through functional studies that PSMA plays a role in tumor angiogenesis and is part of a self-regulating loop that involves β1-integrin and p21-activated kinase 1 (PAK1)." (PMID 38611079, 2024). "In the present study, we demonstrated that tyrosyl phosphorylated PAK1 stimulates tumor growth in mice." (PMID 38660565, 2024). "A recent study has identified PAK1 to contribute to tumor angiogenesis through the HIF1α/VEGF pathway." (PMID 37190165, 2023). "In summary, we have demonstrated in this paper that HCC patients with high PAK1 expression had shorter survival and that PAK1 was crucial in the tumour growth and metastasis of HCC, contributing to resistance to Sorafenib." (PMID 37537668, 2023). "Sorafenib monotherapy reduced the final tumour volume by more than 50% in tumours with low PAK1 levels but only by approximately 30% in tumours with high PAK1 levels." (PMID 37537668, 2023). "In this study of 512 primary BC tumours, we found PAK1 CN ≥4 in 48 (9.4%) cases, of which 22 cases showed high grade CN increase of PAK1 CN ≥6." (PMID 37368917, 2023). "Tumours with high PAK1 levels grew faster and had larger final volumes and weights than those with low PAK1 levels." (PMID 37537668, 2023). "Our data showed that Pak1 abrogation can affect not only cell growth but also tumor-resistant cell invasion." (PMID 37258566, 2023). "Few cases showed PAK1 CN increase in both the primary tumour and the corresponding lymph node metastases." (PMID 37368917, 2023). "Because of its crucial role in tumor metastasis, Rac1/PAK1 is widely used as a target for antitumor treatment." (PMID 37049739, 2023). "Phosphorylation of ATG5 at Thr101 in GBM is positively regulated by PAK1 acetylation, which promotes tumor growth." (PMID 37143582, 2023). "Induction of hepatitis B virus X protein to HCC cells promoted anchorage-independent growth and anoikis resistance by upregulation of PAK1, and knockdown of PAK1 inhibited tumor growth of HCC cells and their resistance to anoikis." (PMID 36672500, 2023). "It is also worth noting that although PAK1 and IFNGR2 satisfy the conditions of HR > 1 and p < 0.05, they are upregulated genes and cannot be considered as tumor risk factors." (PMID 37107646, 2023). "These cell lines showed higher Pak1 expression and phosphorylation levels than sensitive cells, prompting us to investigate the functional role of Pak1 in the onset and maintenance of tumor resistance." (PMID 37258566, 2023). "One study has demonstrated that DEPDC1B can promote tumor cell invasion and migration by activating the Rac1/PAK1/LIMK1/cofilin pathway." (PMID 37049739, 2023). "Cellular and preclinical studies in mice have demonstrated that pharmacological inhibition of PAK1 suppresses PCa tumor growth." (PMID 37190165, 2023). "It is thus possible that the inhibition of RAC signaling would improve anti-tumor immunity and the efficacy of immune therapy, but the role of PAK1 in FasL-mediated killing is yet to be established." (PMID 37830586, 2023). "The inhibition of Rho GDP differentiation inhibitor 2 (RhoGDI2) can also reduce tumor cell migration by downregulating Rac1/PAK1/LIMK1." (PMID 37049739, 2023). "Autophagy-related genes play an important role in tumor progression, and some studies have shown that hypoxia-induced acetylation of PAK1 can enhance autophagy and promote the occurrence of GBM through phosphorylation of ATG5." (PMID 37460467, 2023).
tumor (continued). "TUNEL assays and immunohistochemistry were utilized to determine apoptosis, proliferation, PAK1 and pPAK1 levels in tumour tissues." (PMID 37537668, 2023). "In vivo, both CSF2 silencing and PF3758309 suppressed PAK1-driven tumor proliferation and angiogenesis." (PMID 37564209, 2023). "Of the five cases with PAK1 CN ≥6 in the primary tumour, 3 also had PAK1 CN ≥6 in the corresponding lymph node metastasis." (PMID 37368917, 2023). "Taken together, LIMK1/cofilin is a crucial downstream signaling pathway of Rac1/PAK1 for regulating the rearrangement of actin cytoskeleton and lamellipodia extension of tumor cells." (PMID 37049739, 2023). "IPA-3 is an allosteric inhibitor of p21-activated kinase-1 (PAK-1) that plays an essential role in eukaryotic cell migration, proliferation, and gene transcription, and acts as an anti-tumor target." (PMID 35326881, 2022). "EGFR signaling generally follows the PAK1/Rac1 route to convey the signal and to regulate tumor progression." (PMID 35740379, 2022). "The regulation of PAK1 using small compound inhibitors, shRNA, or miRNA not only suppressed tumor growth but also upregulated the tumor immune response." (PMID 36012284, 2022). "For instance, MLK3 can regulate the Ste20 family member Pak1 kinase and enhance tumor cell proliferation." (PMID 36292671, 2022). "Prior investigations have shown that Pak1/2 promote the proliferation, survival and invasion of tumour cells." (PMID 39899001, 2022). "Further, PAK4 regulates the ratio of M1/M2 tumor-associated macrophages (TAM) through HSPH1, and PAK1 regulates chemotaxis and crawling along the tumor microvessel through LIMK1/Cofilin in neutrophils." (PMID 36230657, 2022). "Evidence has demonstrated that Pak1/2 are upregulated in human tumour tissues, such as breast cancer, gastric cancer, ovarian cancer, and head and neck cancer." (PMID 39899001, 2022). "Recently research determined that ivermectin suppresses tumour growth and metastasis through degradation of PAK1 in ESCC." (PMID 34876051, 2021). "On the one hand, miR-7 targets and downregulates tumorigenic factors in tumour-associated signalling pathways such as PA28γ, EGFR, PAK1, ACK1 and PIK3CD, demonstrating the crucial role of miR-7 in tumour suppression." (PMID 33390839, 2021). "Destabilization of cadherin-dependent junctions by PAK1 activation is consistent with the role of other PAK family members in the adhesion of tumor cell lines and the well-established PAK1 function in promoting tumor migration and metastasis." (PMID 33914026, 2021). "Accordingly, PAK1 depletion decreased tumour incidence rates and size in mice developing spontaneous intestinal-colorectal tumorigenesis." (PMID 33573141, 2021). "More recently, our group has identified alternative BRAF activation of PAK1 to be important in the growth, invasion, and tumor forming effects of BRAFV600E in vitro and in vivo." (PMID 34638434, 2021). "The newly described role of PAK1 in intracellular trafficking is highly significant for known PAK1 functions, such as cell motility, membrane remodeling, and tumor metastasis." (PMID 33914026, 2021). "PDL-1 (a key target for immune checkpoint blockade) expression was reduced in mice tumours via the PAK-1-dependent pathway (p-21 activated kinase 1) activated by Kirsten rat sarcoma (KRAS)." (PMID 34259916, 2021). "As a common PRL and oestradiol (E2) pathway, PAK1 cooperates with ER to stimulate tumour cell metastasis, inducing tamoxifen resistance." (PMID 34651424, 2021). "MLK3 is highly selective, interacting with several effectors, including the Ste20 family member Pak1 kinase, directing its activity and enhancing tumor cell proliferation." (PMID 34511598, 2021). "We have recently reported that PAK1 plays a key role in modulating PSC activity to promote anti-tumour immunity in PDA." (PMID 33126623, 2020).